IL6 (interleukin 6)
Diseases named in the same sentence as IL6 in open-access papers (continued):
Sharing a sentence is not in itself a finding about the gene and the disease.
cervical carcinoma (continued). "Other authors that assessed the levels of IL-6 in cervical cancer tissues and adjacent non-tumor tissues found higher expression in cervical cancer tissues, suggesting its role as a biomarker for the prognosis and therapy of cervical cancer." (PMID 33750983, 2021). "Strikingly, RES can downregulate the expression of IL‐6‐induced P‐Stat3 and its related EMT and ECM‐related biomarkers, and upregulate the expression of epithelial marker E‐cadherin, to inhibit the metastatic potential of cervical cancer cells and play an antitumor role." (PMID 33040485, 2020). "IL‐6 was used to activate STAT3 signaling pathway in HeLa and SiHa cells, and the expression of N‐cadherin, E‐cadherin, vimentin, MMP‐3, and MMP‐13 were examined to confirm the activation of the STAT3 signaling pathway to promote the invasion potential of cervical cancer cells." (PMID 33040485, 2020). "In particular, this study revealed that activation of an IL-6 signaling axis drives the autocrine and paracrine phosphorylation of STAT3 within HPV-positive cervical cancers cells, and that activation of this pathway is essential for cervical cancer cell proliferation and survival." (PMID 31470515, 2019). "Our data demonstrate that AKT contributes to the phosphorylation of p65 and the expression on IL-6 in HPV positive cervical cancer; however, inhibition of AKT only partially reduced IL-6 expression, suggesting alternative components upstream may be involved in NFκB mediated IL-6 expression." (PMID 31226168, 2019). "Thus, IL-6 secreted from HPV positive cervical cancer cells can induce the activation of STAT3 in HPV negative cervical cancer cells via IL-6/gp130 signalling." (PMID 31226168, 2019). "Moreover, IL-6 can induce the expression of vascular endothelial growth factor via the STAT3 pathway, leading to tumor angiogenesis and thereby promoting the development of cervical cancer." (PMID 31297140, 2019). "Furthermore, IL-6 produced by high grade cervical cancer cells regulates not only the increase in expression of MMP-9 but also the decrease of CCR7, normally expressed on immature dendritic cells to ensure their responsiveness to lymph nodes guiding chemokines." (PMID 35408919, 2022). "Antibody-mediated blockade of IL-6 signalling in HPV positive cells inhibits STAT3 phosphorylation, whereas both recombinant IL-6 and conditioned media from HPV positive cells leads to increased STAT3 phosphorylation within HPV negative cervical cancer cells." (PMID 31226168, 2019). "An example of this link is shown by a study reporting that consistently higher expression of IL-6 and VEGF is found in cancerous tissues than in the adjacent noncancerous tissues in early-stage cervical cancer patients." (PMID 31470515, 2019). "Additionally, the activation of the JAK/STAT3 pathway driven by IL‐6 was not identical to the previous prediction that strong STAT3 activation is representative in cervical high‐grade lesions and then withdraw in cervical cancer within tumor nests." (PMID 33694292, 2021). "Importantly, cervical cancer expresses one of the highest amounts of IDO, and both IL-6 and IDO are negative prognostic markers in patients diagnosed with this neoplasm, highlighting the IDO/IL6 axis as an important self-immunoregulatory network in cervical cancer." (PMID 36405719, 2022).
Crohn disease (169 papers, 2006 to 2025). A gastrointestinal disorder characterized by chronic inflammation involving all layers of the intestinal wall, noncaseating granulomas affecting the intestinal wall and regional lymph nodes, and transmural fibrosis. "Linear regression models revealed significant associations between salivary IL-6 and IL-10 with Crohn’s disease; however, those associations were diminished after adjusting the model for age, DMFT, BOP%, and medication use." (PMID 38246944, 2024). "We confirmed that genetic liability to Crohn’s Disease and high IL-6/IL-6Rα levels were causally associated with alterations in TH or SA in some brain regions, which further corroborated the organoleptic connection of the gut-brain axis." (PMID 37153572, 2023). "Third, our study can only suggest a causal association between Crohn’s disease, IL-6 and IL-6R and alterations in cerebral cortical structures." (PMID 37153572, 2023). "Like TNFα, IL-6 is upregulated in Crohn’s disease (CD) especially in patients associated with Mycobacterium avium paratuberculosis (MAP) infection, and both cytokines have been targeted as a therapeutic option for the treatment of the disease despite the accepted partial response in some patients." (PMID 39170608, 2024). "This may explain the excessive increase in IL-6 level in conditions associated with Crohn’s disease, RA, Tuberculosis, and most recently in SARS-CoV-2." (PMID 33072191, 2020). "Moreover, TCZ is expected to be potentially useful in the treatment of other IL-6 associated diseases such as Crohn's disease." (PMID 24839573, 2014). "The associated reduction in waist circumference implied the loss of central adiposity, which has been associated with intestinal inflammation through production of inflammatory cytokines such as TNF‐⍺ and IL‐6 from creeping fat seen in Crohn's disease." (PMID 39967287, 2025). "When peptidoglycan is transferred across the intestinal epithelial cells, it interacts with macrophages, triggers IL-6 secretion and induces inflammation and fibrosis in Crohn’s disease and CRC." (PMID 39641861, 2025). "In turn, high levels of serum interleukin (IL)-6, IL-17A, IL-23, and interferon-γ are commonly observed Crohn’s disease patients, especially when they are at the active state of the disease." (PMID 38246944, 2024). "A phase 2 trial of the anti-IL-6 antibody PF-04236921 or IL-6 pathway blockage in Crohn's disease patients showed reduced disease activity." (PMID 38890719, 2024). "Blocking of IL-6 or its receptors with monoclonal antibodies effectively inhibited progression of Crohn's disease." (PMID 36975838, 2023). "The disease activity in Crohn’s disease (CD) and UC patients has been connected with serum levels of IL-6, soluble interleukin-2 receptor (sIL-2R), CRP, and FC values." (PMID 37710023, 2023). "Further research found a correlation between IL-6 expression and disease activity in patients with Crohn's disease (CD) and UC." (PMID 36109750, 2022). "Th17 cells were differentiated from CD4 cells obtained from the peripheral blood of healthy controls and Crohn’s disease patients, upon in vitro exposure to IL-6, IL-1β, and TGF-β5,18,22." (PMID 36131123, 2022). "The pathogenesis of Crohn’s disease is mainly related to the inflammatory response dominated by cytokines IL-1, IL-6, IL-8, TNF-α and IFN-γ secreted by Th1 and Th17 cells." (PMID 35979355, 2022). "ED suppressed the levels of mucosal inflammatory cytokines, specifically reducing the production of cytokines like TNF-α and IL-6 in the mucosa in patients with Crohn’s disease." (PMID 34626918, 2021). "Like in current study, pro-inflammatory cytokines (IL-1β and IL-6) and chemokine (IL-8) were downregulated, and this was demonstrated ex vivo with heparinized blood of exposed Colitis Ulcerosa, Crohn’s Disease and normal patients." (PMID 34886904, 2021).
Crohn disease (continued). "Anti-TNFα therapy up-regulated IL6 and IL23p19, in patients with Crohn’s disease; IL-1B and IL17A remained up-regulated in patients refractory to anti-TNF α." (PMID 33193322, 2020). "We employed Mycobacterium avium paratuberculosis (MAP) infection in Crohn’s disease (CD) as a model to demonstrate the role of Notch-1/IL-6 signaling on MCL-1 based apoptosis and intracellular MAP infection and persistence." (PMID 33072191, 2020). "Our data are in agreement with previous reports showing that oral supplementation of Ab improved Crohn's disease through the reduction of systemic pro-inflammatory cytokines such as IL-1β, IL-6 and G-CSF." (PMID 32714320, 2020). "On the contrary, in the advanced lesions of Crohn’s disease, marked up-regulation of IL-17A and induction of IL-23 and IL-6 were observed." (PMID 31941937, 2020). "Tocilizumab, a humanized monoclonal anti-IL-6R antibody that is an FDA-approved drug for rheumatic arthritis and Crohn’s disease, competitively binds to both soluble and membrane-bound IL-6 receptors and blocks the intracellular IL-6 signaling pathway." (PMID 30927911, 2019). "Studies have shown that the levels of IL-6 are increased in the serum and the intestinal mucosa of patients with active Crohn's disease." (PMID 31886308, 2019). "A pilot phase II study using the neutralising anti-IL-6R antibody tocilizumab suggested a clinical response in Crohn’s disease (CD) patients, and several inhibitors of the IL-6 pathway are in clinical development, some also for IBD." (PMID 29748708, 2018). "Some studies found that levels of cytokines such as IL-1, IL-6, and IL-8 were higher in patients with Crohn's disease." (PMID 26904110, 2016). "In patients with Crohn disease, high concentrations of IL-6 are present in the serum and intestinal tissue." (PMID 24670876, 2014). "One phenomenon occurring in DSS-treated TC-PTP+/− mice as well as in patients with Crohn's disease is the over-production of IL-6." (PMID 20111595, 2010). "In Crohn's disease and experimental colitis, a role has been suggested for IL-6 trans signaling in mediating the inhibition of apoptosis in lamina propria T cells." (PMID 16859518, 2006). "Moreover, tacrolimus has shown efficacy in related conditions, such as Crohn’s disease, where it suppresses IL-12/IL-23 p40, IL-6, and TNF-α production by activated macrophages." (PMID 40757951, 2025). "Additionally, neutralizing antibodies against cytokines such as TNF-α, IL-6, and IL-12 have demonstrated efficacy in immune-mediated conditions, including Crohn’s disease." (PMID 40564127, 2025). "Although the patient's IL-6 levels are normal at present, her level at the time of active Crohn's disease or prior disseminated histoplasmosis is unknown as is whether either played a role in the development of CD." (PMID 40018696, 2025). "Earlier studies also indicated that human beta-defensins (hBDs), which are chemotactic to T cells and induce the mRNA expression of IL-1β, IL-6, and IL-22, may have copy number variations in Crohn’s disease." (PMID 38246944, 2024). "Indeed, the increase of CEMIP expression is observed after stimulation with TNF-α in OA chondrocytes, IL-6 in Crohn’s disease fibroblasts and IL-1β in pancreatic ductal adenocarcinoma cell line." (PMID 35474501, 2022). "High levels of IL-6 were reported in Castleman’s and Crohn’s disease as well as in RA patients, suggesting GLI3 may play a role in these diseases." (PMID 35937499, 2022). "In OA synoviocytes and in Crohn’s disease fibroblasts, IL-6 significantly up-regulated CEMIP level." (PMID 35474501, 2022). "The pro-inflammatory cytokine IL-6 is highly expressed in the serum of patients with Crohn’s disease (CD), and blocking IL-6 expression may provide benefit to patients with CD." (PMID 36142699, 2022). "In order to prevent this unintended response of ILC, simultaneous blocking of IL-17A and IL-6 may be considered as a potential strategy in the treatment of Crohn’s disease." (PMID 31941937, 2020).
Crohn disease (continued). "We propose that IL-6 as a potential target for Crohn’s disease." (PMID 31941937, 2020). "Additionally, clinical trials showed that fructo-oligosaccharides, a type of fiber that is abundant in vegetables, reduced the IL-6 levels of intestinal dendritic cells in patients with active Crohn’s disease compared with placebo treatment." (PMID 33171846, 2020). "ATG16L1 polymorphisms together with the excessive production of IL-1β and IL-6 in human peripheral mononuclear cells may account for the chronic inflammatory process in Crohn’s disease." (PMID 33020418, 2020). "Blocking the function of IL-17A may upregulate Il6 and recruit RORγt+ ILCs in chronic colitis, thereby upregulating IL-22 and worsening the clinical outcomes of patients with Crohn’s disease." (PMID 31941937, 2020). "Mice rendered genetically deficient in SALSA have increased expression of inflammatory cytokines such as TNF, IL6, and NOD, and humans naturally deficient in SALSA are at increased risk of developing Crohn's disease, further suggesting that SALSA functions to dampening inflammation." (PMID 31850379, 2019). "Moreover, butyrate decreases the intestinal expression levels of tumor necrosis factor-α, IL-1b, and IL-6 in patients with Crohn’s disease." (PMID 28904265, 2017). "The reduced PTPN22 levels contribute to increased levels of IL-6 found in Crohn's disease." (PMID 26734582, 2015). "It is not clear how B cells influence autoinflammatory disorders such as NOMID and Crohn disease; one possibility may be that B cell activation and antibody production in these conditions are bystander effects of IL-6 activity." (PMID 24180594, 2013). "Several studies have found that the levels of TNF and IL-6 are increased in the serum and the intestinal mucosa of patients with active Crohn’s disease, and are positively correlated with the clinical disease activity and histopathological signs of inflammation in Crohn’s disease patients." (PMID 36139127, 2022). "Blockade of IL-6 trans-signaling led to beneficial T-cell apoptosis in the colon of mice with chronic intestinal inflammation, since an enhanced T-cell resistance against apoptosis may contribute to disease perpetuation in Crohn’s disease." (PMID 31694340, 2019). "Moreover, the level of IL-6 is positively correlated with the clinical disease activity, frequency of relapses, and the severity of endoscopic and histopathological signs of inflammation in Crohn's disease." (PMID 31886308, 2019). "Resveratrol has been shown to reduce the levels of proinflammatory mediators such as interleukin 1β (IL-1β), interleukin 6 (IL-6), TNF-α, and TGF-β1 in a rat model of Crohn’s disease." (PMID 38001807, 2023). "ELISA was carried out to examine the expression of TNF-α, IL-1β, IL-6, CRP, SSA, AAT, AAG and HPT in the peripheral blood of patients with Crohn’s disease." (PMID 35422450, 2022). "Similar to the association with poor ICI efficacy, an important observation was that a high interleukin-6 (IL-6) level after ICI treatment was closely related to irAEs, such as Crohn’s disease and psoriasiform dermatitis." (PMID 33317597, 2020). "Increased serum levels of the inflammatory cytokines IL-6 and IL-12, the chemokines MCP-1, MIP-1b, RANTES, and eotaxin, and the soluble IL-2 receptor distinguished among CRMO patients, individuals with Crohn’s disease and healthy controls." (PMID 29080202, 2017). "In addition, IL-6 blockade has shown efficacy in reversing cytokine release syndrome, a clinical by-product of excessive immune activation seen with adoptive T cell therapies, and has also shown preliminary efficacy against Crohn’s disease in an early pilot trial." (PMID 27595932, 2016). "One study reported a significant decrease in proinflammatory cytokines (IL-1, IL-6 and TNF-α) after HBOT in 7 patients with Crohn's disease." (PMID 22417628, 2012).
Crohn disease (continued). "Crohn's disease, a chronic autoimmune-mediated inflammatory bowel disease, induces sustained activation of T-cells and macrophages and elevates pro-inflammatory cytokines such as TNF-α, IL-6, and IL-17." (PMID 41523441, 2025). "When the gingival crevicular fluid Th17 cytokine protein expressions were analyzed in Crohn’s patients, similar expression profiles of IL-1β, IL-6, IL-10, IL-12p40, IL-12p70, IFN-γ, and tumor necrosis factor (TNF)-α were observed in Crohn’s disease patients and in systemically healthy controls." (PMID 38246944, 2024). "Patients with Crohn’s disease display defective innate immune responses and present with an inflammatory macrophage population that produces large amounts of pro-inflammatory cytokines such as TNF-α and IL-6." (PMID 36139127, 2022). "In another study in a murine model of Crohn's disease, UCN could control inflammatory diseases by inhibiting a wide range of inflammatory cytokines such as TNF-α, IFN‐γ, IL-6, IL-1α, IL-1β, IL-12, IL-18, IL-17, and IL-15." (PMID 35419072, 2022). "Indeed, we show that STAT1 transcripts levels are increased in Crohn’s disease and SLE patients and they contributed to alter IL-6 responses." (PMID 33871355, 2021). "However, anti-IL-6 monoclonal antibodies are under trial for the treatment of SLE and Crohn’s disease." (PMID 29662489, 2018). "Also, p38 activation and IL-6 secretion by antigen presenting cells play a huge role in differentiation of CD4+ T cells into Th17 cells, which induces Crohn's disease pathogenesis." (PMID 26734582, 2015). "Noteworthy, we have also tested various other combinations of important cytokines with implication in Crohn's disease (e.g. IL-1ß, IL-6) but failed to induce apoptosis (data not shown)." (PMID 22251670, 2012). "Additionally, increased expression of TLR3 and TLR4 was reported in RA patients and TLR4 was upregulated in Crohn’s disease, suggesting GLI3 may regulate the pathology of Crohn’s disease and RA through modulation of IL-6." (PMID 35937499, 2022). "Interestingly we found that, while creeping fat releases higher levels of leptin, IL-6 and TNFα compared to the MAT explants obtained from Crohn's disease patients, incubation with VSL#3-CM conter-regulates the production of these inflammatory mediators and abrogates the generation of leptin." (PMID 21829567, 2011).